NPTXR (neuronal pentraxin receptor)
Description:
May be involved in mediating uptake of synaptic material during synapse remodeling or in mediating the synaptic clustering of AMPA glutamate receptors at a subset of excitatory synapses.
Synonyms: NPR
Tractability: Antibody: UniProt predicts a signal peptide or a membrane-spanning region; the Human Protein Atlas places it where antibodies can reach. PROTAC: UniProt records ubiquitination sites on it; ubiquitination databases record sites on it; its protein half-life has been measured.
Gene: Protein-coding gene on chromosome 22 (38,818,452 to 38,844,028, reverse strand). Ensembl gene ENSG00000221890.
Subcellular location: Membrane
Subcellular location (Human Protein Atlas): Cytosol; Plasma membrane; Nucleoplasm
Gene Ontology:
Cellular component: glutamatergic synapse; membrane
Genetic constraint (gnomAD): Loss-of-function variants: 14 observed, 26.84 expected, observed/expected ratio (o/e) 0.52, 90% interval 0.34 to 0.81. The synonymous counts are far from expectation, so gnomAD's model fits this gene poorly and the ratio says little. Missense variants: 612 observed, 549.38 expected, observed/expected ratio (o/e) 1.11, 90% interval 1.04 to 1.19. Synonymous variants: 323 observed, 258.17 expected, observed/expected ratio (o/e) 1.25, 90% interval 1.14 to 1.37.
Homologues: Orthologues: chimpanzee NPTXR (99% identical), macaque NPTXR (99% identical), pig NPTXR (93% identical), dog NPTXR (93% identical), mouse Nptxr (88% identical), rat Nptxr (87% identical), guinea pig NPTXR (57% identical), rabbit NPTXR (51% identical), zebrafish cbx6b (12% identical), zebrafish cbx6a (12% identical), Caenorhabditis elegans set-31 (8% identical), Caenorhabditis elegans hpl-1 (2% identical). Paralogues in human: CBX6 (16% identical), CBX8 (11% identical), CBX2 (10% identical), CBX4 (8% identical), CBX7 (6% identical), CBX1 (4% identical), CBX5 (3% identical), CBX3 (3% identical).
Diseases named in the same sentence as NPTXR in open-access papers:
NPTXR is named in the same sentence as 29 diseases in open-access papers, as found by Europe PMC text mining. Sharing a sentence is not in itself a finding about the gene and the disease. The quoted sentences say what the papers report.
dementia (8 papers, 2021 to 2025). Loss of intellectual abilities interfering with an individual's social and occupational functions. "The potential biomarker of NPTXR was also validated in the van Steenoven, Koel-Simmelink (2020) study, which reported that the expression of CSF NPTXR was low in PD and even lower in dementia with Lewy bodies." (PMID 41327336, 2025). "Moreover, the authors revealed that the levels of NPTXR changed with the dementia severity and progression." (PMID 34640593, 2021). "Top proteins with high feature importance in the clinical impairment signature again highlighted ACHE and NPTXR as well as additional targets linked to neuroplasticity (EPHA4 and CNTFR) and immune activation (MSMP and KLK3), underscoring their potential for transdiagnostic dementia staging." (PMID 40665048, 2025). "Overall, these results reflect an increase of NPTX1 and NPTXR in pre-symptomatic stages of genetic AD, MCI and early stages of AD, whereas they decrease in later dementia stages." (PMID 34460014, 2022). "In addition, the behaviour of NPTX1 and NPTXR could be explained by the biphasic activity of the glutamatergic system in the hippocampus, with increased activity in MCI, followed by a decline during the dementia stage." (PMID 34460014, 2022). "The decreased levels of NPTXR allow for differentiation of dementia patients, as well as those with MCI and AD, from controls (p = 0.002 and p = 0.013, respectively), but not between both dementia stages (p = 0.536)." (PMID 37685973, 2023).
Cognitive impairment (5 papers, 2019 to 2025). Abnormal cognition is characterized by deficits in thinking, reasoning, or remembering. "Thus, an increase of these miRNAs would reduce the levels of NPTX1 and NPTXR and could contribute to the glutamatergic synaptic dysfunction and early cognitive impairment present in AD prior to neurodegeneration." (PMID 31092279, 2019). "We identified and positively validated five novel proteins (NCAM2, NPTXR, NRXN2, RELN, and CNTN2) as promising biomarkers for cognitive impairment following aSAH." (PMID 35602555, 2022). "Proteins that could distinguish cognitive impairment were mainly neuronal proteins (VGF, NPTX2, NPTXR, and SCG2)." (PMID 37160957, 2023). "Similarly, NPTXR and NPTX2, neuronal pentraxins that regulate glutamatergic synaptic transmission and synapse formation, were significantly decreased, indicating progressive synaptic dysfunction and excitatory neurotransmission deficits characteristic of AD-related cognitive impairment." (PMID 41292640, 2025).
cognitive decline (3 papers, 2022 to 2026). "In line with reports of reduced CSF NPTX2 in AD and FTD associated with cognitive decline, the decrease of NPTXR in CJD suggests early synaptic degeneration driven by PrPSc‐induced toxicity." (PMID 41574640, 2026). "Synaptic biomarkers like neuronal pentraxins (NPs), including neuronal pentraxin 2 (NPTX2), and neuronal pentraxin receptor (NPTXR), offer insights into FTD pathology and cognitive decline." (PMID 38249293, 2023).
Alzheimer disease (2 papers, 2025). A progressive, neurodegenerative disease characterized by loss of function and death of nerve cells in several areas of the brain leading to loss of cognitive function such as memory and language. "Both proteins have been suggested as potential biomarkers for the synapse loss in Alzheimer's disease, and decreasing levels of NPTXR in CSF has been shown to correspond with more severe Alzheimer's disease pathology." (PMID 40491829, 2025).
gastric cancer (2 papers, 2020 to 2021). A primary or metastatic malignant neoplasm involving the stomach. "Silencing NPTXR using a monoclonal Ab against NPTXR inhibits gastric cancer cell proliferation and leads to cell apoptosis." (PMID 34683129, 2021).
melanoma (2 papers, 2011 to 2022). A malignant, usually aggressive tumor composed of atypical, neoplastic melanocytes. "Furthermore, this core-DEG also contained two neuronal genes, NPTXR and SSTR5, suggesting that melanoma stem cell properties might also have a role in ICI therapy resistance." (PMID 35269844, 2022).
neuroblastoma (2 papers, 2019 to 2020). Neuroblastoma (NB) is the most common solid, extracranial childhood tumor. "They found that blockade of ligand-receptor connection between NPTX2 and NPTXR reduces tumor burden in orthotopic mouse models of human neuroblastoma." (PMID 32847597, 2020). "The NPTX2/NPTXR system was shown to be upregulated in neuroblastoma and promote tumor development." (PMID 30833544, 2019). "NPTXR and NPTX2 are overexpressed in human Schwannian stroma-poor neuroblastoma, and NPTX2 expression serves as a marker of poor prognosis of neuroblastoma patients." (PMID 32847597, 2020).
age-related macular degeneration (1 paper, 2024). Age-related loss of vision in the central portion of the retina (macula), secondary to retinal degeneration. "Five of these proteins (protein-coding genes ECI1, LCT, and NPTXR for glaucoma, WARS1 for age-related macular degeneration (AMD), and SIGLEC14 for diabetic retinopathy (DR)) are newly reported." (PMID 39408566, 2024).
frontotemporal dementia (1 paper, 2019). Frontotemporal dementia (FTD) comprises a group of neurodegenerative disorders, characterized by progressive changes in behavior, executive dysfunction and language impairment, as a result of degeneration of the medial prefrontal and frontoinsular cortices. "Several biomarker discovery studies using mass spectrometry methods have identified changes in CSF levels of NPTX2 or NPTX1 in AD and decreased Neuronal Pentraxin Receptor in Frontotemporal Dementia." (PMID 31853477, 2019).
glaucoma (1 paper, 2024). Increased pressure in the eyeball due to obstruction of the outflow of aqueous humor. "A total of 11 unique protein-coding genes posterior probability (PP) of H4 > 0.70 finally remained, including GSTM3 for senile cataract, WARS1, C3, IGFBP7, and PILRA for AMD, ECI1, LCT, and NPTXR for glaucoma, EFEMP1 for myopia, and SIRPG and SIGLEC14 for DR." (PMID 39408566, 2024).
Huntington disease (1 paper, 2022). Huntington disease (HD) is a rare neurodegenerative disorder of the central nervous system characterized by unwanted choreatic movements, behavioral and psychiatric disturbances and dementia. "We also reported differential expression of proteins involved in glutamate signalling: protein shisa-6 (SHISA6) and neuronal pentraxin receptor (NPTXR) were both downregulated in Huntington’s disease mice and regulate AMPA immobilization and synaptic clustering." (PMID 36523271, 2022).
prion disease (1 paper, 2026). A transmissible disease that is caused by a protein that is able to induce abnormal folding of normal cellular proteins, leading to characteristic spongiform brain changes, which are associated with neuronal loss without an inflammatory response. "Our findings extend this evidence, indicating that peripheral NPTXR reduction may serve as a feasible marker of synaptic pathology in prion disease." (PMID 41574640, 2026).
Stroke (1 paper, 2019). Sudden impairment of blood flow to a part of the brain due to occlusion or rupture of an artery to the brain. "Of these, APLP1, NPTXR, ACTN1 also were detected in the brain tissue of CI/R-induced stroke mice." (PMID 30645580, 2019).
tumor (7 papers, 2019 to 2025). "We found that high NPTXR expression was significantly associated with male sex, macroscopic Borrmann type 4 or 5, pathological T4, and undifferentiated tumor type." (PMID 32847597, 2020). "We investigated the expression and function of NPTXR by in vitro and in vivo analysis of human GC cell lines, tumor xenograft mouse models, and Nptxr-deficient (Nptxr−/−) mice." (PMID 32847597, 2020). "There were 253 genes (13.6%) that had decreased expression shared across tumor types, including NPTXR, SCG2, B4GAT1, and ATRN." (PMID 36909536, 2023). "Having established that anti-NPTXR pAbs suppress tumor growth in vitro and in vivo, we next generated mouse mAbs against the same NPTXR sequence (161–178 CESGLPRGLQGAGPRRDT) as that used to raise pAb-1." (PMID 32847597, 2020). "Few peritoneal nodules were observed in the mice treated with anti-NPTXR pAbs, whereas many large tumor nodules were present in the omentum and mesenteric tissue in mice treated with control IgG." (PMID 32847597, 2020).
cancer (4 papers, 2020 to 2023). A tumor composed of atypical neoplastic, often pleomorphic cells that invade other tissues. "As a second method to explore cancer-related pathways, we performed antibody array analysis to identify alterations in the phosphorylation of intracellular signaling proteins GC cells with loss of NPTXR expression or function." (PMID 32847597, 2020). "Consistent with the paucity of information on the roles of NPTXR in oncogenesis, little is known about the interactions between NPTXR and cancer-related pathways." (PMID 32847597, 2020). "To assess the potential anti-cancer therapeutic value of Ab-mediated blockade of NPTXR in GC and to determine the optimal antigenic site, we next generated and tested pAbs." (PMID 32847597, 2020). "In ROC curve analysis of the ability of NPTXR levels to predict cancer-related mortality, the AUC was 0.651 and the optimal cut-off value was 0.0086." (PMID 32847597, 2020). "To determine whether NPTXR KO affects the presence of GC subpopulations with cancer stem cell-like properties, we examined ALDH levels and found that ALDH was reduced in the KO-1 and KO-2 cells compared with the control MKN1 cells." (PMID 32847597, 2020). "Next, we probed the potential anti-cancer mechanism of action of anti-NPTXR mAb-1." (PMID 32847597, 2020). "We also showed that the anti-cancer effects of the mAbs in vivo resulted from NPTXR antagonism rather than as mediators of ADCC." (PMID 32847597, 2020).
neurodegenerative disease (2 papers, 2021 to 2024). A disorder of the central nervous system characterized by gradual and progressive loss of neural tissue and neurologic function. "Recent studies have shown that NPTXR is a novel biomarker for the progression of neurodegenerative diseases such as AD, and CSF NPTXR levels decrease with the severity of AD." (PMID 38367123, 2024). "Furthermore, as both NEFM, NPTXR, VGF and AQP4 have been implicated in other neurodegenerative disease in addition to FTD, it cannot be stated here that the profiles of the proteins included in the panel are specific for FTD." (PMID 34838088, 2021).
nervous system diseases (1 paper, 2019). "Extensive studies have revealed the importance of the NPTX2/NPTXR axis in nervous system diseases, involving recruitment of glutamate receptors and formation of synapses." (PMID 30833544, 2019).
NPTXR also shares sentences with these, for which no sentence is quoted: breast carcinoma (5 papers); ovarian carcinoma (3); Anxiety (1); diabetic retinopathy (1); endometrial cancer (1); glioblastoma (1); myeloma (1); myopia (1); Obesity (1); osteoarthritis (1); osteoporosis (1); psychiatric disorder (1).